TNF (tumor necrosis factor)
Diseases named in the same sentence as TNF in open-access papers (continued):
Sharing a sentence is not in itself a finding about the gene and the disease.
rheumatoid arthritis (continued). "Substantial progress has been made in the medical management of rheumatoid arthritis (RA) over the past decade with the introduction of biologic therapies, including anti-tumour necrosis factor alpha (anti-TNFα) therapy medications." (PMID 21232112, 2011). "In patients with rheumatoid arthritis, treatment with TNFα antibodies demonstrably reduces joint erosions." (PMID 21403891, 2011). "Anti-TNF-α therapies have been applied to a variety of autoimmune disorders, such as rheumatoid arthritis, inflammatory bowel disease and systemic lupus erythematosus." (PMID 21305012, 2011). "Anti–tumor necrosis factor (anti-TNF) agents are successful therapies in rheumatoid arthritis (RA); however, inadequate response occurs in 30–40% of patients treated." (PMID 21061259, 2011). "Medical history included severe rheumatoid arthritis, for which she had received treatment with anti–tumor necrosis factor-α (TNF-α) for 1 year." (PMID 21392437, 2011). "Treatment with TNF blockade agent adalimumab led to a decrease in serotonin-transporter binding by up to 20% by using [123I]β-CIT-SPECT in a group of patients with rheumatoid arthritis." (PMID 21418592, 2011). "TNF-α is the cytokine as the target for development of new medications development for disease involving inflammation, such as rheumatoid arthritis." (PMID 19745004, 2011). "For instance, TNF-α primes lung fibroblasts to produce Th1 type chemokines in interstitial lung diseases, and in rheumatoid arthritis, TNF-α stimulates secretion of matrix metalloproteinases by synovial fibroblasts." (PMID 20657842, 2010). "The role of TNF α in autoimmune diseases is well known, and it is currently a target for monoclonal antibody in diseases such as rheumatoid arthritis." (PMID 21159177, 2010). "The success of anti-TNF biologics for the treatment of rheumatoid arthritis has highlighted the importance of understanding the intracellular pathways that regulate TNF production in the quest for an orally-available small molecule inhibitor." (PMID 20230629, 2010). "Infliximab a chimeric monoclonal antibody against TNF-α that has been introduced for patients with Crohn's disease, rheumatoid arthritis, psoriasis, juvenile chronic arthritis and more recently for BD patients who were resistant to standard treatment." (PMID 20525258, 2010). "Infliximab is a high affinity monoclonal anti TNF-α antibody that has been introduced for Crohn's disease and rheumatoid arthritis treatment in patients who are resistant to standard therapy." (PMID 20525258, 2010). "In the clinic, TNF-α inhibitors are being used with success in the treatment for rheumatoid arthritis, psoriatic arthritis, and Crohn’s disease." (PMID 21152396, 2010). "Anti-tumor necrosis factor (TNF)-α biotherapies have considerably changed the treatment of rheumatoid arthritis (RA)." (PMID 20633267, 2010). "Whilst it is difficult to dissect the biological meaning of statistical epistatic models, it should be noted that several lines of evidence support a role for Fcγ receptors and IRF5 in rheumatoid arthritis and TNF driven processes." (PMID 20691091, 2010). "Tumor necrosis factor (TNF) is a pivotal cytokine in the inflammatory synovium of patients with rheumatoid arthritis (RA)." (PMID 20535785, 2010). "The SDR method was then applied to a series of 386 Dutch patients with active rheumatoid arthritis that were treated with anti-TNF biological agents." (PMID 20691091, 2010). "The TGF- pathway, for example, shows broad, constitutive alternation in Rheumatoid Arthritis Synovial Fibroblasts (RASFs) and the NF-B pathway has been inhibited during the anti-TNF- therapy by etanercept." (PMID 20419126, 2010). "Anti-tumor necrosis factor-alpha (anti-TNFα) therapy, such as inflixamab, is now commonly used to treat rheumatoid arthritis and Crohn’s disease." (PMID 20885786, 2010).
rheumatoid arthritis (continued). "There has been significant progress in the treatment of rheumatoid arthritis (RA), particularly with the development of anti-TNFα therapy." (PMID 20525198, 2010). "The expression of TNF-α and IL-1β is especially elevated during an acute phase of rheumatoid arthritis." (PMID 23675204, 2010). "Recently, anti-TNF therapy resulted in reduced serum MIF levels in patients with rheumatoid arthritis." (PMID 21152395, 2010). "The associations between other cytokines and bone health have also been assessed; TNF-α is associated with bone resorption, as is IL-17, which is reported to act synergistically with TNF-α to promote bone turnover in rheumatoid arthritis patients." (PMID 22254049, 2010). "TNF-α is expressed in the synovial lining cells and is present in the synovial fluid from patients with rheumatoid arthritis (RA) or osteoarthritis (OA)." (PMID 20691044, 2010). "A range of them are currently licensed as TNFα-blocking agents and are being used in the management of inflammatory diseases, including rheumatoid arthritis, ankylosing spondylitis and Crohn's disease, with a varying degree of success." (PMID 20463923, 2010). "Given their established efficacy and safety profile, biologic agents that neutralize TNF-α have received approval from the USA Food and Drug Administration for the treatment of rheumatoid arthritis." (PMID 19641635, 2009). "The development of TNF-alpha blockers in the treatment of psoriasis, psoriatic arthritis, rheumatoid arthritis, Crohn's disease and ankylosing spondylitis have been major breakthroughs." (PMID 20101303, 2009). "No definitive data are available regarding the value of switching to an alternative TNF antagonist in rheumatoid arthritis patients who fail to respond to the first one." (PMID 19627609, 2009). "In the ReAct (Research in Active Rheumatoid Arthritis) trial, Bombardieri and colleagues evaluated the effectiveness and safety of adalimumab in RA patients who previously discontinued TNFα antagonists for any reason." (PMID 19886983, 2009). "Immunosuppressants, including anti-TNFα antibodies, have remarkable effects in rheumatoid arthritis; however, they increase infectious events." (PMID 19900268, 2009). "In comparison with rheumatoid arthritis, SF levels of TNF-α in ReA are lower despite comparable levels of IL-2 receptor, again implicating a relative deficiency of protective antimicrobial cytokines in the local environment." (PMID 19203382, 2009). "In a more recent cohort study, rheumatoid arthritis patients on either methotrexate or tumour necrosis factor alpha (TNF-α) inhibitors, were twice as likely to develop bladder cancer as the general population." (PMID 19773763, 2009). "Rheumatoid arthritis (RA) is a multifactorial chronic inflammatory joint disease that involves secretion of proinflammatory cytokines such as tumour necrosis factor-α (TNF-α), interleukin 1 (IL-1), and IL-6 which are associated with local inflammation and a systemic reaction." (PMID 19946428, 2009). "Infliximab, a chimeric monoclonal immunoglobulin antibody to tumor necrosis factor-α, has been established as a safe and effective treatment of rheumatoid arthritis, active and fistulising crohn's disease." (PMID 19946518, 2009). "Anti-TNF therapy has been applied to various types of serious inflammatory disease, such as rheumatoid arthritis, Crohn's disease, ankylosing spondylitis, and spondylarthropathy, as well as to degenerative disease of the intervertebral disc." (PMID 19916697, 2009). "TNFα plays a critical role in the pathogenesis of rheumatoid arthritis and psoriasis, and DCs are the primary source of TNFα." (PMID 22399974, 2009). "Rituximab (RTX) is a monoclonal antibody against CD20 used in cases of rheumatoid arthritis that fail to respond to anti TNF agents." (PMID 23675123, 2009).
rheumatoid arthritis (continued). "Anti-tumor necrosis factor (TNF) therapies have been widely and successfully used several chronic autoimmune diseases, such as rheumatoid arthritis (RA) and Crohn's disease." (PMID 20003451, 2009). "Passive blockade of tumor necrosis factor-alpha (TNF-α) has demonstrated high therapeutic efficiency in chronic inflammatory diseases, such as rheumatoid arthritis, although some concerns remain such as occurrence of resistance and high cost." (PMID 20030816, 2009). "Infliximab is a chimeric monoclonal antibody against tumor necrosis factor-alpha (TNF-α) used in the treatment of rheumatoid arthritis (RA); its efficacy was demonstrated in a randomized controlled trial." (PMID 19939280, 2009). "First, rheumatoid arthritis is the most prevalent autoimmune inflammatory diseases for which anti–TNF-α therapies are approved." (PMID 19861045, 2009). "In our review, most patients with anti–TNF-α–related NTM were elderly women with rheumatoid arthritis." (PMID 19861045, 2009). "Similar situations are reported in rheumatoid arthritis patients treated with the TNF-α antagonist etanercept, or even in solid organ transplant patients under a high dose of immunosuppression." (PMID 19830176, 2009). "TNF-alpha blocking agents have been used extensively in rheumatology primarily in the treatment of rheumatoid arthritis." (PMID 20016776, 2009). "The inflammatory cytokine, tumor necrosis factor-alpha is a well known inflammatory protein, and has been a therapeutic target for the treatment of diseases such as Rheumatoid Arthritis and Crohn's Disease." (PMID 19558671, 2009). "We report a case of a 53 year old lady recently commenced on etanercept, an anti-TNF (tumour necrosis factor) therapy for rheumatoid arthritis presenting with confusion, pyrexia and an erythematous rash." (PMID 19046446, 2008). "Under pathological conditions, serum TNFα levels can be as high as 53 pg/ml in advanced stage of cancer, or even 368 pg/ml in rheumatoid arthritis patients." (PMID 18275606, 2008). "RNA was extracted from peripheral blood mononuclear cells of 19 rheumatoid arthritis patients before the first application of the TNFα blocker etanercept as well as after 72 hours." (PMID 18454843, 2008). "In a disease such as rheumatoid arthritis (RA), the pathological roles of pro-inflammatory cytokines such as TNFα, interleukin (IL)-1β, and IL-6 have been demonstrated." (PMID 18493620, 2008). "Therapy with cytokine modulators and antagonists is increasingly practised in many countries, beginning with anti-TNF antibodies for rheumatoid arthritis and Crohn's disease, and now for many other indications." (PMID 19014537, 2008). "Blockade of TNFα activity using monoclonal antibodies or the soluble TNFα receptor has been used as an effective therapy in rheumatoid arthritis, inflammatory bowel disease and severe asthma." (PMID 18510721, 2008). "Both the anti-TNF drugs infliximab and etanercept have been shown to be beneficial in rheumatoid arthritis and psoriasis." (PMID 18331642, 2008). "Anti tumor necrosis factor agents are a valuable addition to the armamentarium against rheumatoid arthritis but have some serious side effects which clinicians should be aware about." (PMID 18973686, 2008). "This study approached a problem of major clinical and socio-economic importance: the efficacy and safety of anti-TNFα drugs in the treatment of rheumatoid arthritis (RA)." (PMID 18419803, 2008). "Anti tumor necrosis factor (TNF) agents are emerging in the frontline management of rheumatoid arthritis (RA) in the current era of biologicals." (PMID 18973686, 2008). "There are currently 3 anti–tumor necrosis factor α (anti-TNFα) drugs licensed for use in rheumatoid arthritis (RA) in the UK: infliximab and adalimumab, both monoclonal antibodies, and etanercept, a TNFα receptor fusion protein." (PMID 17763441, 2007).
rheumatoid arthritis (continued). "Several biologic inhibitors (antibodies and receptor fusion molecules) have been developed that interfere with TNF activity and are used to control inflammation in diseases such as rheumatoid arthritis and Crohn's disease." (PMID 17953477, 2007). "Locally produced proinflammatory cytokines such as tumor necrosis factor-α, interleukin (IL)-1, and IL-6 play a pivotal role in the pathology of rheumatoid arthritis (RA)." (PMID 17511858, 2007). "For example, blockade of tumor necrosis factor-α (TNFα) is now widely used to treat human rheumatoid arthritis." (PMID 23675028, 2007). "TNF-α shares modes of actions with several other pro-inflammatory cytokines but experiences from treating rheumatoid arthritis patients with TNF-α inhibitors suggests that this cytokine is of unique and critical importance in chronic inflammatory disorders." (PMID 23675033, 2007). "Transgenic mice expressing human TNFα (hTNFα) have previously been described as a model for progressive rheumatoid arthritis." (PMID 18070349, 2007). "Inhibition of tumour necrosis factor (TNF)-alpha with biological molecules has proven an effective treatment for rheumatoid arthritis, achieving a 20% improvement in American College of Rheumatology score in up to 65% of patients." (PMID 17254348, 2007). "Recently a clinical trial on patients with rheumatoid arthritis showed increased serum endostatin levels after a single injection of a TNF-α antibody." (PMID 16839420, 2006). "TNF derived from mast cells also plays a crucial role in initiation of inflammation, particularly in the case of rheumatoid arthritis." (PMID 16518473, 2006). "Many approaches have been investigated to inhibit TNF activity for the treatment of various inflammatory/autoimmune diseases (e.g., rheumatoid arthritis, Crohn disease, and inflammatory bowel disease)." (PMID 16518473, 2006). "Due to proinflammatory and prooxidative actions, TNFα complicates many diseases, the most important of which are atherosclerosis, rheumatoid arthritis, psoriasis, inflammatory bowel disease, Alzheimer's disease and various pulmonary disorders." (PMID 17034639, 2006). "Macrophages play an important role in both chronic inflammation and joint destruction in rheumatoid arthritis (RA), principally by producing many proinflammatory cytokines such as tumour necrosis factor-α (TNF-α)." (PMID 16859503, 2006). "Actually, TNFα-blockage with antibodies has been of unquestionable clinical benefit to many patients with rheumatoid arthritis, Crohn's disease, psoriasis and, more recently, ankylosing spondilitis." (PMID 16507146, 2006). "Therapy with anti-tumour necrosis factor (TNF) alpha is effective for rheumatoid arthritis (RA), with an estimated 500,000 patients being treated worldwide." (PMID 15899041, 2005). "Agents such as infliximab, which neutralize the effects of TNF-α, are currently in clinical use for the treatment of rheumatoid arthritis and Crohn's disease." (PMID 16168106, 2005). "The present study was set up to investigate the number and nature of clinically important dermatological conditions during TNF-α-blocking therapy in patients with rheumatoid arthritis (RA)." (PMID 15899052, 2005). "Infliximab and etanercept, used as anti-TNFα agents for rheumatoid arthritis and Crohn's disease, are rather reported to induce demyelination." (PMID 15813970, 2005). "Neutrophils are known to be targets for the biological activity of tumour necrosis factor (TNF)-α in the pathogenensis of rheumatoid arthritis (RA)." (PMID 15743471, 2005). "Tumour necrosis factor (TNF)-α has been found to play a central role in the pathogenesis of rheumatoid arthritis (RA), which has led to the rational development of novel drug therapies that neutralize the deleterious effects of this cytokine." (PMID 15743471, 2005). "This is supported by the overwhelming effects of TNF blockade, which has revolutionized the therapy of rheumatoid arthritis (RA)." (PMID 15642137, 2005).
rheumatoid arthritis (continued). "We have previously used monoclonal antibodies against TNF to ameliorate disease in animal models of arthritis as well as rheumatoid arthritis in the clinic." (PMID 15026813, 2004). "TNFα overexpression has also been directly implicated in chronic inflammatory diseases, including inflammatory bowel disease (IBD)—which encompasses Crohn's disease (CD) and ulcerative colitis (UC) —, rheumatoid arthritis (RA), and psoriasis." (PMID 41551713, 2026). "Tumor necrosis factor-α (TNF-α) is an important inflammatory mediator and has been widely recognized as a diagnostic biomarker for various autoimmune and infectious diseases in clinical practice, such as rheumatoid arthritis." (PMID 41728025, 2026). "Studies have revealed that cytokines such as RORγt, IL-17A, and IL-21 expressed in the mucosa not only contribute to inflammatory bowel disease but also lead to elevated mRNA levels of IL-17A, IL-22, and TNF-α in knee joint tissues, which was observed in mouse models of rheumatoid arthritis." (PMID 41400824, 2026). "While essential for normal functions like neurogenesis and tissue repair, overproduction of TNF-α is a key driver in autoimmune diseases (like rheumatoid arthritis and Crohn’s) and other conditions, leading to the development of anti-TNF therapies that block its action." (PMID 41596367, 2026). "Because PG and rheumatoid nodules are difficult to distinguish, the use of TNF‐α inhibitors, which may benefit cutaneous and pulmonary manifestations, may be a promising strategy when clinically appropriate." (PMID 41573269, 2026). "In rheumatoid arthritis, miRNA modulation influenced TNF-α signaling." (PMID 41535614, 2026). "In patients with ACS who also have rheumatoid arthritis (RA), TNF-α expression on atherosclerotic plaques is even stronger, suggesting a more intense and sustained pro-inflammatory response that may worsen outcomes." (PMID 41511355, 2025). "Similarly, anti-TNF therapies including etanercept, infliximab, and adalimumab are commonly used in the treatment of autoimmune diseases such as rheumatoid arthritis, Crohn’s disease, psoriatic arthritis, and psoriasis." (PMID 40564127, 2025). "In vivo pharmacodynamics studies found that general conditions, microcirculation indices, synovial histopathology, and expression of related proteins in the synovial tissue of rheumatoid arthritis rabbits were effectively alleviated by mEXOs‐TNF‐α siRNA cryoMNs." (PMID 40837042, 2025). "In rheumatoid arthritis, IL-17 cooperates with TNF and IL-6 to promote synovial fibroblast activation, RANKL upregulation, and erosive damage with synovial tissue atlases identifying Th17-related inflammatory neighborhoods that may modulate treatment response." (PMID 41303386, 2025). "Additionally, anti-TNF therapy has been successful in other kinds of autoimmune diseases like Rheumatoid Arthritis, Psoriatic Arthritis, and Spondyloarthropathies." (PMID 40507454, 2025). "The established efficacy of TNF blockade in other chronic arthritides, such as rheumatoid arthritis and spondyloarthritis, suggests a shared inflammatory pathway that may also contribute to persistent FMF-related arthritis." (PMID 41333465, 2025). "Understanding the stage-specific actions of TNFα could provide new perspectives for therapeutic interventions in diseases characterized by excessive osteoclast activity, such as rheumatoid arthritis." (PMID 40688496, 2025). "In addition, KEGG enrichment analysis identified pathways such as the “IL-17 signaling pathway”, “TNF signaling pathway” and “Rheumatoid arthritis”." (PMID 40102753, 2025). "Enriching the TNF signalling pathway and the rheumatoid arthritis pathway indicates that these genes may be pivotal in inflammatory responses and autoimmune disorders." (PMID 40475773, 2025). "Similarly, in rheumatoid arthritis, dysregulated cytokine signaling—particularly involving TNF-α and IL-6—results in persistent joint inflammation and autoimmunity." (PMID 40364844, 2025).